IGF1R (insulin like growth factor 1 receptor)
Diseases named in the same sentence as IGF1R in open-access papers (continued):
Sharing a sentence is not in itself a finding about the gene and the disease.
oral cancer (11 papers, 2016 to 2025). "Increased IGF‐1 receptor (IGF‐1R) expression is associated with malignancy and tumour growth in different cancer types, including paraganglioma and oral carcinoma." (PMID 34528373, 2021). "Molecular docking and molecular dynamics simulations revealed that quercetin binds tightly to the core targets (THBS1, SERPINE1, and IGF1R) of nicotine‐related oral carcinoma, suggesting its potential as a therapeutic agent for oral cancer." (PMID 41368332, 2025). "In vitro experiments demonstrated that quercetin can inhibit the expression of the core targets (THBS1, SERPINE1, and IGF1R), thereby suppressing the proliferation and metastasis of both nicotine‐transformed cells and oral cancer cells." (PMID 41368332, 2025). "Fibroblasts derived from OSF contribute to increased migration and invasion, inducing an epithelial–mesenchymal-like state by upregulating IGF1R in oral cancer cells." (PMID 38059910, 2023). "The protein levels of the IGF‐1R were upregulated specifically in fBMF CM treatment for oral cancer cells, and the IGFR gene was confirmed by The Cancer Genome Atlas patient transcriptome data." (PMID 34528373, 2021). "miR-99a overexpression inhibited IGF1R expression and suppressed migration and invasion in vitro in oral cancer OEC-M1 and CGHNC9 cells." (PMID 28708091, 2017). "IGF1R is a target of miR-99a, and is frequently overexpressed in oral cancer and the IGF induced repression of miR-99a." (PMID 28708091, 2017). "miR-99 family contributes to oral cancer tumorigenesis by targeting IGF1R and mTOR signaling pathways." (PMID 29206174, 2017). "On the contrary, overexpression of hsa-miR-99a distinctly inhibited cell proliferation and induced apoptosis by down-regulating the expression level of IGF1R and mTOR genes in oral cancer cells." (PMID 26933913, 2016). "Finally, OSF activates the epithelial to mesenchymal transition of OSCC, thus promoting the EMT-induced invasion by upregulating IGF-1R expression in human oral cancer (IGF-1R is increased in OSCC patients)." (PMID 40565504, 2025). "Two of its potential targets were identified in oral cancer, namely Igf1R and Irs-2." (PMID 29206174, 2017). "IGF1R inhibitor may suppress the migration and invasion of oral cancer cells." (PMID 28708091, 2017). "Through network pharmacology studies, additional gene targets of quercetin for treating nicotine‐related oral carcinoma, such as THBS1, IGF1R, and SERPINE1, were identified." (PMID 41368332, 2025). "A total of 29 genes shared by quercetin and nicotine‐related oral carcinoma were screened, and SERPINE1, IGF1R, and THBS1 were identified as hub genes." (PMID 41368332, 2025). "Several studies including immunotherapeutic strategies and inhibitors of VEGFR, IGF-1R, PI3K/AKT/mTOR and MET have been conducted, being expected in a near future a shift in the management of oral cancer patients towards more personalized treatment." (PMID 27895714, 2016). "Thus, IGF‐1 was elevated in OSF and, consequently, increased the expression of IGF‐IR and promoted the EMT and invasion by upregulating IGF‐1R in human oral cancer." (PMID 34528373, 2021).
synovial sarcoma (11 papers, 2013 to 2025). "A more recent study showed treatment of synovial sarcoma cells with dasatinib also led to apoptosis, decreased proliferation, and was associated with reduced phosphorylation of IGF-1R, AKT and Stat3." (PMID 25236161, 2014). "Higher IGF-1R expression has also been associated with more aggressive synovial sarcoma." (PMID 23383402, 2013). "For instance, targeting the heparanase/heparan sulfate proteoglycan system using a supersulfated low molecular weight heparin (ssLMWH) inhibited cell colony growth and downregulated the IGF1R in synovial sarcoma preclinical models." (PMID 34440844, 2021). "Significantly, SS18–SSX and IGF1R cooperate in synovial sarcoma malignancy, playing important but different roles in maintaining malignant growth of synovial sarcoma cells." (PMID 34440844, 2021). "Similarly, functional studies in synovial sarcoma cell lines have linked the expression of the SS18::SSX fusion transcript to levels of YAP/TAZ, which have been mechanistically linked to IGF-1R/PI3K/AKT signalling." (PMID 40983796, 2025). "The IGF2/IGF1R/Akt-MAPK axis drives synovial sarcoma cells growth and migration." (PMID 34440844, 2021). "Dysregulation of IGF1R signaling in synovial sarcoma might also depend on additional mechanisms." (PMID 34440844, 2021). "Accordingly, ihibition of IGF1R signalling using the TKI NVP-AEW541-impaired phosphorylation of Akt and MAPK, increased apoptosis, diminished mitotic activity and migration of synovial sarcoma cells." (PMID 34440844, 2021). "In preclinical studies, all of 15 synovial sarcomas tested showed significant IGF-II expression and 78% showed activated IGF-1R." (PMID 23383402, 2013).
adenoma (10 papers, 2010 to 2025). A neoplasm arising from the epithelium. "The type 1 insulin-like growth factor receptor (IGF1R) has been implicated in various aspects of adenoma development and metastasis." (PMID 21811251, 2011). "Overexpression of IRS1, together with ß-catenin, InsRß, and IGF1R, in FAP-associated adenomas was in agreement with data reported for the Apc(Min/+) mouse model." (PMID 22558377, 2012). "This suggests that, in the setting of chronic blockade of EGFR, activation of the IGF1R pathway is mediating adenoma growth through alternative, unidentified mechanisms." (PMID 21811251, 2011). "Chronic monotherapy against either EGFR or IGF1R influences adenoma growth, but combination EGFR/IGF1R blockade produced the most effective adenoma suppression." (PMID 21811251, 2011). "We have confirmed the significance of early gefitinib induced IGF1R signalling in colon adenomas in relation to resistance as IGF1R and IGF1R phosphorylation are increased at the protein level in chronic gefitinib exposed resistant adenomas." (PMID 21811251, 2011). "We show here that acute administration of gefitinib inhibits EGFR signalling while also activating the IGF1R pathway in adenomas developing in the Apcmin/+ mouse, an in vivo physiologically relevant model of intestinal tumourigenesis." (PMID 21811251, 2011). "To address this approach, we determined if the acute activity in IGF1R predicted improved outcome (in terms of anti-adenoma effect) when IGF1R inhibition was combined with EGFR blockade." (PMID 21811251, 2011). "If the level of phospho-ERK is crucial in driving IGF1R resistant adenomas, then the acute data showing an increase in phospho-ERK potentially reflects a mechanism of resistance." (PMID 21811251, 2011). "In terms of understanding the mechanism of the adenoma suppression with combined EGFR/IGF1R treatment, we undertook protein analysis for 4 h following EGFR and IGF1R blockade alone and in combination." (PMID 21811251, 2011). "Notably, the IGF-1R protein levels differed significantly between adenoma and CRC." (PMID 35931997, 2022). "In demonstrating EGFR blockade enhanced IGF1R activity we have provided support for the in vivo proof of concept that IGF1R-targeted therapy may induce an anti-adenoma effect in adenomas expressing high receptor levels driven by continued EGFR blockade, and is a potential predictive biomarker." (PMID 21811251, 2011). "IHC indicated that IGF-1R and Livin protein levels are increased in CRC and adenoma tissues compared to normal tissues." (PMID 35931997, 2022). "IRS1 mRNA and protein resulted higher, relative to paired mucosa, in adenomas of familial adenomatous polyposis patients and in CRCs that overexpressed c-MYC, ß-catenin, InsRß, and IGF1R." (PMID 22558377, 2012). "This suggests continued EGFR inhibition is required to promote IGF1R adenoma expression and the target of AZ12253801, to elicit an anti-adenoma response." (PMID 21811251, 2011). "The analysis of the IGF1 cascade in the “surgical series” did not showed any difference in IGFBP4, IGF1 and IGF1R mRNA expression in cancer, adenomas and hyperplastic nodules compared to the respective benign counterparts." (PMID 34350538, 2022). "Also, adenomas developed in small intestine shows similar expression of β-catenin and IGF-1R (data not shown)." (PMID 22174655, 2011). "Furthermore, the IHC results showed significantly higher levels of IGF-1R in tubular adenoma, villous adenoma, and CRC tissues compared to the adjacent normal tissues, as assessed by the Mann–Whitney U test, and the difference between adenoma and CRCs was statistically significant." (PMID 35931997, 2022).
Autoimmunity (10 papers, 2015 to 2025). The occurrence of an immune reaction against the organism's own cells or tissues. "More recent studies have shown that miRNAs—also linked to autoimmunity development—are important regulators of IGF1R expression; however, their role should be further investigated." (PMID 34501407, 2021). "Taken together, the study demonstrates that IGF1R is an important control mechanism that prevent development of autoimmunity." (PMID 36105797, 2022). "In experimental model and in patient material, this study demonstrates that IGF1R plays an important role in preventing autoimmunity." (PMID 36105797, 2022). "A different mode of IGF1R dependent autoimmunity has been described in thyroiditis, where IGF1R bearing B cells are responsible for the production of pathogenic antibodies against the thyrotropin receptor." (PMID 36105797, 2022). "Although the causality of this association is unclear, the data imply a potential influence of IGF1R autoimmunity on muscle development." (PMID 31940750, 2020). "These include Tgfb3, which is important in Th17-mediated autoimmunity, Igf1r, which is highly expressed in T-ALL cells, Rsad2 (viperin), which is a regulator of viral infection, Cd24a, which is important in T-cell homeostasis and Dusp16, which is a negative regulator of JNK in T-cells." (PMID 25908851, 2015). "The observed clinical worsening of EAE, also reflected by increased density of inflammatory lesions in IGF-1RKO−tdTomato mice, might thus suggest that IGF-1R signalling in BAMs/microglia exert a significant protective role limiting the development of CNS autoimmunity." (PMID 36890580, 2023). "Thus, insufficient T cell control in the MZ could have created the conditions for autoimmunity observed after IGF1R inhibition in our study." (PMID 36105797, 2022). "Disease incidence was however comparable between experimental groups, thus suggesting that IGF-1R absence did not affect peripheral development of autoimmunity." (PMID 36890580, 2023). "Nevertheless, data on IGF1R gene variations in SS—a disease model of the crossroad between autoimmunity and malignancy—are absent." (PMID 34501407, 2021). "The phenotypic and functional effects of betamethasone was accompanied by changes in the expression of genes related to autoimmunity, metabolism and islet mass, both in NIT-1 cells and islets such as a downregulation of Igf1r and a hyperexpression of Ptprj –both genes related to insulin sensing." (PMID 30718757, 2019). "The extensive and careful investigations on the role of estrogen, estrogen receptors and estrogen metabolites in autoimmunity conducted in RA, SSc and SLE bear repeating in the orbital fibroblasts of patients with thyroid eye disease, as do examinations of estrogen’s effects on IGF-1R." (PMID 35784325, 2022). "Although there is no report about the direct contributory role of IGF1R in AIH yet, recently, its specific modulatory role in autoimmunity was confirmed by researchers in EAE mice." (PMID 37163367, 2023).
depression (10 papers, 2015 to 2023). "Similarly, IGF1/IGF1R signaling declined during pregnancy, which is notable given that IGF1 deficiency in the hippocampus is linked to depression Wnt5a signaling in endothelial cells also declined during pregnancy compared with virgin." (PMID 36239981, 2022). "Adult rats exposed prenatally to stressful stimuli displayed not only depression-like behavior but also decreased IGF-1 expression, dysregulation in the IGFBP network, and diminished mRNA expression, as well as IGF-1R phosphorylation, in the OB." (PMID 26610812, 2016). "Novel object intervention not only increases IGF-1R phosphorylation but also results in increased phosphorylation of CREB and increase in serotonin concentration in the hippocampus that synergistically contribute towards the amelioration of anxiety and depression like traits during monotony stress." (PMID 25880744, 2015).
diabetic kidney disease (10 papers, 2016 to 2025). Progressive kidney disorder caused by vascular damage to the glomerular capillaries, in patients with diabetes mellitus. "The EGFR gene is a cellular growth pathway regulator implicated in diabetic nephropathy while IGF1R can activate cascades of intracellular proteins involved in glucose and lipid metabolism." (PMID 41031259, 2025). "Our findings also suggest a regulatory role of miRNAs in modulating target genes such as AKT1, MMP13, and IGF1R, implicating them in signaling pathways and cellular metabolism relevant to Diabetic Kidney Disease." (PMID 38891851, 2024). "Above results demonstrated that the high glucose‐induced exo‐circ_0125310 promoted cell proliferation and fibrosis in diabetic nephropathy via sponging miR‐422a and targeting the IGF1R/p38 axis." (PMID 34854210, 2022). "Downregulation of IGF1R improved insulin response in diabetic mice and alleviated inflammation of diabetic kidney disease in mice In this study IGF1R was significantly increased when comparing healthy controls and prediabetics, and also when comparing prediabetic with diabetic patients." (PMID 40533788, 2025). "IGF-1 signaling via IGF-1R on MCs may contribute to the pathogenesis of diabetic kidney disease through the induction of Has2 and fibrotic genes." (PMID 39638246, 2024). "IGF-1R may also contribute to the pathogenesis of diabetic kidney disease through the induction of fibrotic genes and hyaluronan synthase 2, a key enzyme involved in the synthesis of hyaluronan, a component of the extracellular matrix." (PMID 39638246, 2024). "Our results suggest that elevated Grb10 expression may play an important role in the pathogenesis of diabetic nephropathy through suppressing IGF-1/IGF-1R signaling pathway, which might be a potential molecular target of catalpol for the treatment of this diabetic complication." (PMID 26986757, 2016). "Insulin-like-growth factor-1 (IGF-1) is the ligand for insulin-like growth factor-1 receptor (IGF-1R), and the roles of IGF-1/IGF-1R in diabetic nephropathy (DN) are well-characterized previously." (PMID 37034500, 2023). "Increased IGF1R and IGFBP in renal tissue was found in the early course of diabetic nephropathy in experimental models as well." (PMID 34943879, 2021). "Mesangial cells isolated from experimental models of diabetic nephropathy exhibit altered IGF1 synthesis, IGF1 pathway activation, and higher IGF1R expression and activation compared with controls." (PMID 34943879, 2021). "Collectively, our findings support the notion that catalpol exerts its therapeutic effects on diabetic nephropathy possibly by down-regulating Grb10 expression and the subsequent activation of IGF-1/IGF-1R signaling." (PMID 26986757, 2016). "Additionally, other IGF-1R inhibitors, including GSK4529, can ameliorate diabetic kidney disease by amelioration of inflammatory infiltration and tubulointerstitial fibrosis by suppressing Snail1 expression." (PMID 37034500, 2023).
invasive breast carcinoma (10 papers, 2012 to 2024). A carcinoma that infiltrates the breast parenchyma. "Our findings provide the rationale for further developing the combination of paclitaxel with IGF blockers for the treatment of invasive breast cancer, and Insulin/IGF1R activation and IGF+ stroma cells as potential biomarker candidates for further evaluation." (PMID 29367764, 2018). "We found that IGF1R was frequently expressed in canine invasive mammary carcinoma, as more than 90 % showed at least a weak membrane staining for IGF1R." (PMID 26449867, 2015). "IGF-1R and Rap1 expressions were both reported to exhibit increased expression in invasive breast cancer, again suggesting that IGF-1R contributes to the invasive switch in cancer." (PMID 26191041, 2015). "Therefore, the optimal combination of membrane-expressed proteins to target by molecular imaging seemed to consist of CD44v6, GLUT1, EGFR, HER2, and IGF1-R by which about 80% of invasive breast cancers are predicted to be detectable." (PMID 22695343, 2012). "Of the 127 selected articles (CAIX, GLUT1, CXCR4 IGF1R), we excluded ten articles from the analysis due to (suspected) overlap of study populations, and one article because we could not distinguish between carcinoma in situ and invasive breast cancer." (PMID 24206539, 2013).